YAP1 (Yes1 associated transcriptional regulator)
Diseases named in the same sentence as YAP1 in open-access papers (continued):
Sharing a sentence is not in itself a finding about the gene and the disease.
hepatocellular carcinoma (continued). "Our study demonstrated that increased nuclear expression of YAP1 could be observed in cholangiocarcinomas (EHBCA and IHCCA) and a subset of hepatocellular carcinomas (CK19(+) HCC) and that nuclear YAP1 expression was correlated with poor overall survival in pT1 stage IHCCA patients." (PMID 28645247, 2017). "Consequently, elevated glucose concentrations may enhance cellular susceptibility to ferroptosis by facilitating the O-GlcNAcylation of YAP1 and ZEB1 in hepatocellular carcinoma (HCC) and pancreatic cancer cells." (PMID 41350524, 2025). "However, a differing pattern of YAP1 expression between cHC-CCAs and CK19(+) HCCs and the poor prognosis of YAP1 positive hepatic carcinomas suggests that YAP1 may have a preferential role in aggressive tumor behavior, rather than in the determination of cellular lineage in hepatic carcinomas." (PMID 28645247, 2017).
lung cancer (105 papers, 2014 to 2025). A malignant neoplasm involving the lung. "We here investigated the functions and the underlying regulatory mechanisms of the two YAP1 isoforms in the context of EGF‐induced epithelial‐mesenchymal transition (EMT) in non‐small cell lung cancer (NSCLC)." (PMID 35014181, 2022). "Along the same lines, YAP1 activation was associated with poor response to treatment with the ALK/ROS1 inhibitor crizotinib in ALK-rearranged lung cancers." (PMID 34685695, 2021). "ASOs targeting ARL4C (ASO-1316) showed decreased RAS-related substrate activity, inhibited cell proliferation and migration, and suppressed nuclear import of Yes-associated protein-1 (YAP-1) in lung cancer cell lines bearing KRAS and EGFR mutations." (PMID 33740988, 2021). "A recent seminal study showed that acquired resistance against Kras inhibition in a Kras-driven mouse lung cancer model was associated with an increased YAP1 signaling; Kras and YAP1 signaling converges and activates the cellular EMT machinery." (PMID 28241877, 2017). "Our data also demonstrated that EGFR mutated or KRAS mutated lung cancers are associated with higher nuclear YAP1 expression in comparison to EGFR/KRAS wild type tumors." (PMID 26716514, 2016). "Both genetic and pharmacological YAP1 inhibition was associated with improved sensitivities to these treatment modalities in lung cancer cells." (PMID 26716514, 2016). "Our GSEA results suggested that high YAP1 expression was associated with reduced activities of DNA repair processes, and defective DNA repair contributes to individual susceptibility to lung cancer development." (PMID 36479120, 2022). "Our results identified the miRNAs associated with brain metastasis of lung cancer and indicate that miR-550a-3-5p and YAP1 may be novel potential targets for controlling brain metastasis." (PMID 34530822, 2021). "Moreover, recent studies addressed the genomic alterations associated with distant metastases, e.g., ESR1 mutations and MYC, YAP1 amplifications enriched in metastatic breast cancer and lung cancer genomes, respectively." (PMID 33287735, 2020). "Moreover, literature data revealed the association between YAP1 levels and OS in gastric, colorectal, hepatocellular, pancreatic, and lung cancer." (PMID 30006603, 2018). "As there were various EGFR mutation subtypes in YAP1 carriers, other second hits may be needed to initiate lung cancer formation." (PMID 27449093, 2016). "Our IHC experiments indicated that EGFR-mutated lung cancers were associated with higher YAP1 activation, thus YAP1-targeted therapy may potentiate the cytotoxicity of erlotinib (tyrosine kinase inhibitor targeting EGFR) in EGFR-mutated NSCLC cells." (PMID 26716514, 2016). "In vitro as well as in vivo studies confirmed that YAP1/WWTR1/TEAD-dependent transcription is acutely activated after osimertinib treatment in EGFR-mutant lung cancer, and pharmacological and genetic ablation of this complex strongly inhibits persister cells." (PMID 40428391, 2025). "The study showed that activation of YAP1/WWTR1/LEPR dependent transcription is a potent factor of osimertinib resistance in EGFR mutant lung cancer." (PMID 40428391, 2025). "YAP1 induces the expression of antiapoptotic factors myeloid cell leukemia sequence 1 (Mcl‐1) and B‐cell lymphoma‐extra large, enhancing lung cancer cell survival." (PMID 40066231, 2025). "We confirmed both in vitro and in vivo that YAP1/WWTR1/TEAD-dependent transcription is acutely activated following osimertinib treatment in EGFR mutant lung cancer and pharmacologic and genetic ablation of this complex strongly suppresses persister cells." (PMID 38658677, 2024). "Conversely, YAP1 inhibition by siRNA or a YAP1 inhibitor, verteporfin, enhanced the response to lorlatinib in lung cancer cells (KTOR71)." (PMID 38499647, 2024). "Previous study has shown that treatment of lung cancer harboring ROS1 fusion with lorlatinib can activate YAP1 in vivo or in vitro." (PMID 38499647, 2024).
lung cancer (continued). "We show that YAP1/WWTR1/TEAD-dependent transcription is acutely activated following treatment of EGFR mutant lung cancer cells with EGFR inhibitors and that prevention of YAP1/WWTR1 activation strongly suppresses cancer cell persistence." (PMID 38658677, 2024). "To this end, we monitored YAP1 phosphorylation in control or PRRG2 stably expressing lung cancer cells." (PMID 38355937, 2024). "FSCN1 has been reported to increase cell glycolysis to promote tumor growth and metastasis through the YAP1-PFKFB3 axis in lung cancer." (PMID 37491232, 2023). "Tumors that escape KRAS suppression in a KRAS-driven murine lung cancer model show high YAP1 activity and upregulation of epithelial-to-mesenchymal transition (EMT)-like transcriptional programs." (PMID 35883668, 2022). "YAP1–HIF1α interaction is notably higher in non–small cell lung cancer (NSCLC) tissues as compared with normal lung, suggesting a novel mechanism by which YAP1 promotes tumor growth." (PMID 35937460, 2022). "The effect of metabolic reprogramming on cancer stem cells via regulation of YAP1 has been demonstrated in lung cancer and CRC." (PMID 35672802, 2022). "Genetic alterations of EGFR, MAP2K1, mTOR, TEAD1, and YAP1 in The Cancer Genome Atlas (TCGA) cohorts of lung cancer occurred at respective frequencies of 15.0%, 1.80%, 6.00%, 1.80%, and 2.50%." (PMID 35655775, 2022). "Further, we analyzed the correlation between the expression of SAV1 and YAP1 in normal lung tissues in the GTEx database as well as normal lung tissues and lung cancer tissues in the TCGA database." (PMID 35864957, 2022). "Because our experiments indicate that YAP1 regulates multiple angiogenic genes and is also upregulated during hypoxia, experiments were conducted to assess if YAP1 contributes to VEGF expression in hypoxic lung cancer cells." (PMID 35937460, 2022). "It was found that the expression of SAV1 and YAP1 was highly and positively correlated in normal lung tissues compared to lung cancer tissues." (PMID 35864957, 2022). "Our analysis of lung cancer context-specific interaction networks of hub genes revealed that deregulated expressions of EGFR/MAP2K1/mTOR/TEAD1/YAP1 in lung cancer mediated abnormal expressions of 151 genes in total in 154 cancer-mediated interactions." (PMID 35655775, 2022). "The transcriptional coactivator YAP1 is the major oncogenic component of the Hippo signaling pathway and contributes to the genesis and progression of various tumors, including non–small cell lung cancer (NSCLC)." (PMID 35937460, 2022). "YAP1 was also proven to be related to the multidrug resistance of lung cancer by CD74-related signaling pathways." (PMID 36428672, 2022). "For example, CCT3 overexpression promoted lung cancer cell growth and migration through regulating YAP1." (PMID 35773623, 2022). "It has been found that knockdown of VHL inhibits tumor progression in lung carcinoma; it remains to be established if this is mediated by YAP1-dependent mechanisms." (PMID 35937460, 2022). "First, KRAS-mutant lung cancer cells underwent verteporfin treatment; KRAS-mutant lung cancer cells also underwent siRNA-mediated knockdown of YAP1." (PMID 33830081, 2021). "In breast, esophageal, and lung cancer tissues, YAP1 expression was lower than that in normal tissue controls." (PMID 34150844, 2021). "Specific EMT regulation induced by YAP1 with oncogenic KRAS was shown in a murine lung cancer model." (PMID 33830081, 2021). "Our findings will help to improve our understanding of the progression of brain metastasis and provide a basis for using miR-550a-3-5p and YAP1 as potential targets for controlling brain metastasis of lung cancer." (PMID 34530822, 2021). "These D5D siRNA-loaded nanoparticles inhibited the proliferation of lung cancer cells and induce apoptosis by suppressing YAP1/TAZ axis." (PMID 33740988, 2021).
lung cancer (continued). "We selected several cancers with the most obvious expression differences between tumor tissues and normal adjacent tissues (breast, pancreatic, colorectal, esophageal, gastric, and lung cancers) and explored the critical role of YAP1 in patient outcomes." (PMID 34150844, 2021). "In lung cancer, for example, YAP1 activation confers resistance to therapies targeted against common lung cancer oncogenes, such as anaplastic lymphoma kinase (ALK), BRAF or mutated epidermal growth factor receptor (EGFR) tyrosine kinase." (PMID 34685695, 2021). "YAP1 was predicted to be the target gene of miR-550a-3-5p in lung cancer cell-derived exosomes, because the 3′-UTR of YAP1 contains the binding site for miR-550a-3-5p." (PMID 34530822, 2021). "The sixth one is hsa-mir-375, which affects YAP1 molecule in lung cancer and is involved in the regulation of multiple lung cancer stages as a target of Claudin-1 in NSCLC." (PMID 32428028, 2020). "Since ivermectin is a compound that targets yes-associated protein 1 (YAP1), it is anticipated to exhibit anti-tumoral effects against ovarian, gastric, colorectal, and lung cancers, for which high expression of YAP1 is thought to be a prognostic indicator." (PMID 33092251, 2020). "YAP1 expression mediated the survival of ALK-rearranged lung cancer cells treated with alectinib by a mechanism involving pro-apoptotic protein regulation." (PMID 31900393, 2020). "We consider combinatorial therapy against ALK and YAP1 to be a promising therapy that enhances treatment effects in ALK-rearranged lung cancer." (PMID 31900393, 2020). "Preveiously, our group have proved that YAP1 KD substantially reduced stem-related genes levels of lung cancer cells." (PMID 32863772, 2020). "COPB2 also reportedly promotes lung cancer cell proliferation and tumorigenesis by upregulating YAP1 expression, and silencing COBP2 significantly inhibits cell proliferation and induces apoptosis in cholangiocellular carcinomas." (PMID 31926110, 2020). "The ectopic expression of YAP1‐6SA at least partially restored the lung sphere formation ability and the proportion of ALDH+ CSC in DGUOK KO cells (and EV4E), suggesting that DGUOK depletion inhibits lung cancer cell stemness by inhibiting YAP1 signaling." (PMID 31633874, 2019). "Lung adenocarcinoma specimens with high DGUOK expression levels also tend to have increased YAP1 staining, which is consistent with the notion that DGUOK regulates YAP1 in lung cancer patients." (PMID 31633874, 2019). "We find that lung cancer cells with RASSF1A promoter methylation display constitutive nuclear YAP1 accumulation and expression of prolyl 4‐hydroxylase alpha‐2 (P4HA2) which increases collagen deposition." (PMID 31268606, 2019). "Several distinct mechanisms have been reported to regulate YAP1-mediated regulation of therapy resistance in lung cancer cells including acquistion of an EMT phenotype and overexpression and/or activating mutations of receptor tyrosine kinases." (PMID 30956771, 2019). "High expression levels of YAP1 were repeatedly reported as a poor prognostic factor, especially in gastric, colorectal, hepatocellular, pancreatic and lung cancer." (PMID 30006603, 2018). "A functional genomic screen identified YAP1 as a key determinant that conferred resistance to EGFR-TKI in lung cancer cells." (PMID 29435131, 2018). "Overexpression of YAP1 in lung cancers led to an increase in ABCG2 expression and increased the percentage of SP cells." (PMID 27911857, 2017). "Our ChIP data indicated that YAP1 directly regulated ABCG2 expression at the transcriptional level in H460 lung cancer cells." (PMID 27911857, 2017). "Finding that EGFR signaling triggers an increase in YAP1 protein expression and its activity, we next focused on understanding the biological roles of YAP1 in EGFR-dependent lung cancer cells." (PMID 29163769, 2017). "Collectively, our findings suggest an important role of the Hippo pathway and YAP1 in lung cancer stem-like cells." (PMID 27911857, 2017).
lung cancer (continued). "YAP1 has been identified as a key determinant to enhance treatment sensitivity to EGFR-targeted therapy in lung cancer." (PMID 29163769, 2017). "This study demonstrated that YAP1 is an important EGFR downstream signaling molecule that is crucial for lung cancer cell proliferation." (PMID 29163769, 2017). "We then showed that both genetic (shRNA or siRNA) and pharmacological YAP1 blockade (verteporfin) improved cisplatin activity in lung cancer cells." (PMID 26716514, 2016). "In summary, the present study provides evidence to identify YAP1 as a key and actionable determinant of sensitivities to platinum, radiation and erlotinib in lung cancer cells." (PMID 26716514, 2016). "To further validate this promising target identified in our screen, we first confirmed that different shRNAs and an siRNA pool targeting YAP1 can efficiently knockdown YAP1 protein expression in the PC9 lung cancer cell line." (PMID 26716514, 2016). "In the present study, we also evaluated the association between YAP1 germline mutation and EGFR mutation status among lung cancer families (Cohort-2)." (PMID 27449093, 2016). "Verteporfin also synergizes with radiation and erlotinib in PC9 lung cancer cells suggestive of a functional synergism upon YAP1 blockade (CI < 1, P < 0.05)." (PMID 26716514, 2016). "miR-375 has been shown to target YAP1 in lung cancer cells and also SEC23A at its 3′-UTR in PC cell lines to regulate cell growth." (PMID 27832783, 2016). "YAP1 knockdown by either shRNA or siRNA indeed quite prominently improved sensitivities to cisplatin in PC9 lung cancer cells in a synergistic manner (CI < 1)." (PMID 26716514, 2016). "Verteporfin indeed reduces phosphorylation of YAP1 in PC9 lung cancer cells at baseline or in the presence of cisplatin, whereas a YES inhibitor, dasatinib had no such effects." (PMID 26716514, 2016). "It has been also reported that hsa-mir-375 was related to YAP1 in lung cancer, and its activation was consider to be involved in cancer progression." (PMID 26099552, 2015). "To this end, we first confirmed the interaction between PRRG2 and YAP1 in lung cancer cells." (PMID 38355937, 2024). "The observed significant overexpression of TWIST1 and positive correlation with YAP1 in both chronic inflammatory patients and lung cancer patients may be attributed to forced expression of YAP1 that elevated TWIST1 mRNA and protein." (PMID 38589525, 2024). "Therefore, after exogenously expressing YAP1 gene, we analyzed the differential expressed genes (DEGs) that were up-regulated in normal lung epithelial cells but remained unchanged in lung cancer cells." (PMID 35864957, 2022). "Studies have also found that YAP1 plays a crucial role in CSCs in lung cancer and prostate cancer." (PMID 35672802, 2022). "Amplification of the YAP1 gene drives lung cancer brain metastasis." (PMID 35885905, 2022). "The results in vitro and in vivo showed that G2, a pharmacological inhibitor of fascin-1, could significantly reduce the levels of PFKFB3 and YAP1 in lung cancer cells and nude mice." (PMID 36033434, 2022). "However, our findings therefore suggest the pro-apoptotic switch in the role of EGFR and YAP1 during lung cancer metastasis." (PMID 35655775, 2022). "In addition, YAP1 transcriptional regulators are known to upregulate the EMT activity of lung cancers, but YAP1 expression is enriched in limited-stage tumors with an inflamed phenotype." (PMID 36428693, 2022). "We performed small-molecule library screening and identified verteporfin, a yes-associated protein 1 (YAP1) inhibitor; verteporfin treatment markedly reduced cell viability in KRAS-mutant lung cancer cells in vitro and suppressed KRAS-driven lung tumorigenesis in vivo." (PMID 33830081, 2021). "Taken together, exosomal miR-550a-3-5p may control the progression of lung cancer with brain metastasis by targeting YAP1 expression." (PMID 34530822, 2021). "YAP1 has been confirmed to be account for therapeutic resistance in lung cancer." (PMID 33336871, 2021).